SYK (spleen associated tyrosine kinase)
Diseases named in the same sentence as SYK in open-access papers (continued):
Sharing a sentence is not in itself a finding about the gene and the disease.
Arthritis (18 papers, 2009 to 2026). Inflammation of a joint. "As a cytoplasmic tyrosine protein, SYK plays an important role in the pathophysiology of diseases associated with allergic inflammation and hyper-responsiveness, such as asthma and arthritis, and has been predicted to be an attractive target for therapeutic kinase inhibitors." (PMID 31466385, 2019). "Thus, both JAK and SYK signaling pathways are involved in early pathogenic mechanisms of arthritis and simultaneous inhibition of both kinases results in greater efficacy." (PMID 26653844, 2015). "Syk has been recently implicated in arthritis pathogenesis and joint damage, and Syk-deficient mice are protected from autoantibody-induced erosive arthritis, and treatment with a SYK inhibitor significantly reduced disease severity and joint erosions and damage in collagen-induced arthritis." (PMID 23249408, 2012). "Our interest in SYK was further provoked by the contrasting effects of its blockade in mouse models and clinical trials in arthritis." (PMID 29497423, 2018). "The greatest effects were observed with the dual inhibition of JAK + SYK, which prevented all mice from developing arthritis." (PMID 26653844, 2015). "We have showed greater efficacy of dual versus single JAK and SYK inhibition in a chronic model of arthritis." (PMID 26653844, 2015). "Overall, our data show that dual JAK + SYK inhibition is efficacious and has a good safety profile, and therefore can be seen as a candidate treatment strategy in arthritis." (PMID 26653844, 2015). "To test the efficacy of dual JAK + SYK inhibition, we chose a novel and well-accepted murine model of arthritis induced by the systemic antigen G6PI." (PMID 26653844, 2015). "In a mouse SYK p.Ser544Tyr mutant model corresponding to human SYK p.Ser550Tyr, histological examination of the mice's tails revealed an increase in immune cells and signs of arthritis." (PMID 37506139, 2023). "Thus the aim of this study was to characterize the mechanism of action and efficacy of a small molecule multikinase inhibitor MT-SYK-03 targeting SYK and cSrc kinases among others in different in vitro and in vivo arthritis models." (PMID 34848799, 2021). "Simultaneous JAK + SYK inhibition completely prevented mice from developing arthritis." (PMID 26653844, 2015). "Single inhibition of SYK led to the development of milder arthritis." (PMID 26653844, 2015). "Thus, dual JAK + SYK inhibition also presents greater efficacy than anti-TNF treatment in this experimental model of severe arthritis." (PMID 26653844, 2015). "Therefore, concurrent JAK + SYK inhibition ameliorates clinical, immunological and histological parameters of arthritis." (PMID 26653844, 2015). "The results suggest inhibition of SYK kinase activity may prevent bone erosion in arthritis, which is consistent with previous SYK knockout mice studies." (PMID 24286216, 2013). "Blocking of SYK could inhibit the immune complex-mediated inflammation in arthritis." (PMID 35967305, 2022). "Thus, both JAK and SYK mediate memory cell pool maintenance and, thus, their inhibition could maintain disease remission and prevent arthritis recurrence." (PMID 26653844, 2015). "For example, fostamatinib, a selective inhibitor of spleen tyrosine kinase (SYK), suppressed clinical arthritis and bone erosions in a mouse model of arthritis." (PMID 27094362, 2016). "Concurrent JAK + SYK inhibition resulted in higher efficacy than single kinase inhibition and TNF blockade in a chronic and severe arthritis model." (PMID 26653844, 2015). "Potential immunotoxicity was also evaluated in G6PI-induced arthritis and in a 28-day TDAR model, by analysing the effects of JAK + SYK inhibition on hematological parameters, lymphoid organs, leukocyte subsets and cell function." (PMID 26653844, 2015). "Under these conditions, inhibition of SYK resulted in a minimal (non-significant) decrease of arthritis parameters." (PMID 26653844, 2015).
Arthritis (continued). "Efficacy of dual JAK + SYK inhibition with selective small molecule inhibitors was evaluated in chronic G6PI-induced arthritis, a non-self-remitting and destructive arthritis model in mice." (PMID 26653844, 2015). "Inhibition of JAK, but not SYK, was able to stop disease progression, and after 2 weeks of treatment started to mildly reduce arthritis severity." (PMID 26653844, 2015). "To this end, we used potent and selective small molecule inhibitors of pan-JAKs (tofacitinib) and SYK (PRT062607) either in combination or alone, which were tested, for the first time, in a destructive and non-remitting arthritis murine model." (PMID 26653844, 2015).
acute myeloid leukemia (16 papers, 2015 to 2026). Acute myeloid leukemia (AML) is a group of neoplasms arising from precursor cells committed to the myeloid cell-line differentiation. "Especially, based on the important function of SYK in hematopoietic cells, the therapeutic action of SYK inhibitors has been confirmed in multiple myeloma, such as acute myeloid leukemia and chronic lymphocytic leukemia." (PMID 36568669, 2022). "SYK is a kinase inhibitor therapeutic target for acute myeloid leukemia." (PMID 36430822, 2022). "Spleen tyrosine kinase (SYK) is an important oncogene and signaling mediator activated by cell surface receptors crucial for acute myeloid leukemia (AML) maintenance and progression." (PMID 33159047, 2020). "An integrated transcriptomic and survival analysis led to the identification of SYK and HDAC isoforms as age- and FLT3-dependent prognostic markers in acute myeloid leukemia (AML)." (PMID 42262889, 2026). "Contrarily, in B-cell lymphocytic leukemia (B-CLL), diffuse large B-cell lymphoma (DLBCL), follicular lymphoma, mantle cell lymphoma, marginal zone lymphoma (MZL), B-cell acute lymphocytic leukemia (B-ALL), acute myeloid leukemia (AML), SYK performed as a tumor promoter gene." (PMID 34575665, 2021).
atherosclerosis (15 papers, 2013 to 2026). A disease characterized by the build-up of fatty material and calcium deposition in the arterial wall resulting in partial or complete occlusion of the arterial lumen. "In a rodent model, they observed that high glucose levels and the progression of atherosclerosis were associated with elevated cardiac spleen tyrosine kinase (SYK) activity." (PMID 38255703, 2024). "We tested the effect of the SYK inhibitor fostamatinib on hypercholesterolemia-associated myelopoiesis and plaque formation in Apoe−/− mice during early and established atherosclerosis." (PMID 26891724, 2016). "SYK inhibition demonstrates significant anti-proliferative effects on vascular smooth muscle cells, attenuating cell proliferation and migration associated with atherosclerosis development." (PMID 41544081, 2026). "Module and GO enrichment analysis identified an additional gene, SYK, which may affect atherosclerosis risk via a similar mechanism." (PMID 39276247, 2024). "The long-term effects of this SYK inhibitor on cardiovascular events in this high risk study population with chronic inflammation and accelerated atherosclerosis remains unknown." (PMID 26891724, 2016). "SYK is a critical mediator involved in atherosclerosis progression through inflammatory signaling pathways." (PMID 41544081, 2026). "An experimental study has shown that treating mice with SYK inhibitors significantly reduced atherosclerosis lesions in atherosclerosis-prone mice." (PMID 39276247, 2024). "Our findings also suggest that the GM-CSF receptor/SYK/JNK/FOXO1/CD11c signaling axis is commonly involved in the development of atherosclerosis and chronic inflammation." (PMID 37520709, 2023). "SYK plays a critical regulatory role in the inflammatory process of atherosclerosis, such as oxidized lipid deposition, C-reactive protein, NF-κB activation, platelet activation, and inflammatory body activation." (PMID 34777534, 2021). "SYK has been reported to be involved in the pathogenesis of atherosclerosis by activating monocyte chemotactic protein-1 expression." (PMID 26742467, 2016). "We used Syk-knockout atherosclerosis-prone mice to determine whether SYK is involved in atherosclerosis via the inflammatory response and elucidate the mechanism of SYK signaling." (PMID 37520709, 2023). "Several other nodes in the module (e.g., LYN and SYK) are druggable, have atherosclerosis phenotypes in mice, and have preferable target tissues and thus may be interesting targets for new CAD therapies." (PMID 29467471, 2018). "The validation study also indicated SYK was up-regulated both at the level of mRNA and protein which strengthens the assertion that it might play an important role in atherosclerosis development." (PMID 26742467, 2016). "The present study compared the efficacy of SYK inhibition in early and established atherosclerosis." (PMID 26891724, 2016). "Because BEP-CE is present in human plasma and human atherosclerotic lesions, BEP-CE-induced and TLR4/SYK-mediated macrophage responses may contribute to chronic inflammation in human atherosclerosis." (PMID 24376657, 2013). "Combining bioinformatics prediction with target gene expression analysis, we found in this study that miR‐129‐2‐3p may be involved in the pathogenesis of IS by regulating the expression of SYK gene, which is a critical regulator in the development of atherosclerosis." (PMID 30499219, 2019). "We hypothesized that SYK inhibition by fostamatinib would reduce monocytosis and cell adhesion, and provide us with a tool to lower monocyte contribution to the plaque in early and late atherosclerosis." (PMID 26891724, 2016). "Inhibition of SYK or CDKN1A might prevent against atherosclerosis development." (PMID 25333956, 2014). "Several studies have indicated important related functions for SYK and VAV1, suggesting that they play significant roles in atherosclerosis." (PMID 26742467, 2016).
atherosclerosis (continued). "This study identified SYK, LYN, PTPN6 and the “FcεRI-mediated signaling pathway” as potential candidate players involved in the pathogenesis of atherosclerosis." (PMID 26742467, 2016). "Downregulated genes (SYK, SMAD3, S100A4, and FERM3) were expected to be involved in inhibiting cellular recruitment by IPA, and were previously documented to enhance the beginning and progression of atherosclerosis." (PMID 35806463, 2022). "The analysis revealed that a similar representation of the gene expression patterns of our candidate DEGs was seen in the dataset GSE28829, suggesting that VAV1, SYK, LYN and PTPN6 genes may play an important role in progression of atherosclerosis." (PMID 26742467, 2016). "Thus, GM-CSF receptor/SYK/JNK/FOXO1/CD11c signaling in monocytes and macrophages and FOXO1 could be therapeutic targets for atherosclerosis and inflammatory diseases." (PMID 37520709, 2023). "Although SYK carries out several functions, such as inflammatory cytokine production, phagocytosis of oxidized LDL, and cell differentiation, its involvement in the shared pathophysiology between atherosclerosis and chronic systemic inflammatory diseases remains unclear." (PMID 37520709, 2023). "6-week-old Apoe−/− mice, still devoid of atherosclerosis, consumed a high cholesterol diet (HCD) supplemented with or without 0.3 % (w/w) SYK inhibitor fostamatinib for 8 weeks." (PMID 26891724, 2016).
immune thrombocytopenia (15 papers, 2019 to 2025). "Sovleplenib is also a SYK inhibitor, shows a promising durable response in patients with primary immune thrombocytopenia." (PMID 39736771, 2024). "In 2018, a small molecule inhibitor of SYK known as fostamatinib was approved for the treatment of immune thrombocytopenia." (PMID 31226783, 2019). "However, the experience regarding the SYK inhibitors in the clinical trials for hematological malignancies and the clinical practice for immune thrombocytopenia (ITP) is that the hematological toxicity, i.e., bone marrow suppression, is quite low." (PMID 36499034, 2022). "Overall, a better characterization of the SYK phosphorylation signaling pathways in different tissue types is crucial because pharmacological SYK inhibitors are now used in the clinic to treat immune thrombocytopenia, autoimmune hemolytic anemia and IgA nephropathy." (PMID 33670716, 2021). "Thus, SYK inhibitors are being developed to treat allergic disorders as well as antibody-mediated autoimmune diseases such as allergic rhinitis, rheumatoid arthritis, asthma, cancer, diabetes type I, and immune thrombocytopenia among others." (PMID 31226783, 2019). "Spleen tyrosine kinase (SYK) and Bruton’s tyrosine kinase (BTK) inhibitors have emerged as promising targeted therapies for adult immune thrombocytopenia (ITP)." (PMID 41458387, 2025). "An orally active SYK inhibitor, fostamatinib, has already received FDA approval as a treatment for immune thrombocytopenia and continues to be investigated as an experimental therapy for hematological malignancies (NCT00446095)." (PMID 35650195, 2022). "Fostamatinib, a non-selective SYK inhibitor approved in treatment of immune thrombocytopenia, has demonstrated clinical efficacy in NHL." (PMID 35296646, 2022).
ovarian carcinoma (15 papers, 2004 to 2026). A malignant neoplasm originating from the surface ovarian epithelium. "The ratio of phosphorylated SYK vs SYK was found to be positively associated with paclitaxel- resistance in ovarian cancer cells in vitro." (PMID 29719615, 2018). "Except for CD8B, TRAT1 and SYK, all the other module genes were found to be significantly associated with survival of ovarian cancer patients (p < 0.05)." (PMID 26099452, 2015). "For example, high expression of tubulin beta 3 class III (TUBB3) and low expression of salt inducible kinase (SIK2), polo-like kinase 2 (PLK2) or spleen tyrosine kinase (SYK) restore the paclitaxel sensitivity of ovarian cancer cells." (PMID 35477477, 2022). "The microtubule-associated protein (MAP) kinase spleen tyrosine kinase (SYK) has also been shown to mediate chemoresistance to PTX in ovarian cancer, although the understanding of SYK’s function and action is limited." (PMID 33182737, 2020). "In contrast, SYK has been shown to be pro-tumorigenic in prostate cancer, small-cell lung cancer, ovarian cancer, glioma, pediatric retinoblastoma, and Ewing sarcoma." (PMID 30744170, 2019). "SYK methylation was also correlated with poor overall survival of colorectal cancer and SYK is also overexpressed in ovarian cancer." (PMID 29372378, 2018). "Recently, SYK overexpression has been reported in triple negative breast cancers and ovarian cancer." (PMID 29719615, 2018). "A potential tumor suppressor gene SYK is in this cluster; SYK has been identified as a regulator of epithelial cell growth and its splicing pattern alters cell survival in breast and ovarian cancer." (PMID 26939613, 2016). "Notably, eight proteins upregulated in the invasive stroma (NNMT, FCGR1A, FCER1G, TYMP, F13A1, DCK, CASP3, and SYK) represented FDA-approved drug targets outside of ovarian cancer, emphasizing their high relevance for future preclinical investigations." (PMID 41233595, 2026). "Interestingly, a similar pattern has recently been reported in ovarian cancer, where abnormal splicing of SYK supports cancer cell proliferation and survival." (PMID 29861861, 2018). "SYK also plays an important role in ovarian cancer as paclitaxel-resistant cells overexpress SYK." (PMID 29719615, 2018). "We compared hypermethylation of MGMT, CDH1, RAR-β and SYK promoters in ovarian carcinoma (OC)." (PMID 14970867, 2004). "In addition, some taxane-resistant epithelial ovarian cancers express higher levels of the MAPK pathway protein SYK, which is hypothesized to counteract the stabilization of microtubules by taxanes." (PMID 39177285, 2024). "Furthermore, paclitaxel resistant SYK overexpressing ovarian cancer was targeted in pre-clinical models to show that use of chemical inhibitor against SYK could be useful to decelerate tumor activity." (PMID 29719615, 2018). "SYK positively regulates EGFR and has been shown to be involved in EGFR signaling in squamous cells and ovarian carcinoma, where it contributes to paclitaxel and lapatinib resistance." (PMID 37760847, 2023).
chronic lymphocytic leukemia (14 papers, 2014 to 2022). "Tyrosine phosphorylation of SYK is the pathogenic event observed in chronic lymphocytic leukemia (CLL) B-lymphocytes." (PMID 35806271, 2022). "PTP1B was previously shown to dephosphorylate SYK at pY526 in isolated chronic lymphocytic leukemia cells from patients." (PMID 34526379, 2021). "A phase 2 clinical trial with entospletinib, a selective SYK inhibitor, revealed clinical improvement in patients with relapsed or refractory chronic lymphocytic leukemia." (PMID 29137391, 2017). "Interestingly, activation of PKCΔ by SYK was found to be an antiapoptotic driver in chronic lymphocytic leukemia, and the active protein kinase SYK was also observed in follicular lymphoma, DLBCL, and mantle cell lymphoma." (PMID 35158799, 2022). "For example, inhibition of BTK, PI3K and SYK through ibrutinib, idelalisib, and fostamatinib, respectively, has been shown to be effective in follicular lymphoma, mantle cell lymphoma (MCL), and chronic lymphocytic leukemia (CLL)." (PMID 29489886, 2018).
melanoma (14 papers, 2007 to 2025). A malignant, usually aggressive tumor composed of atypical, neoplastic melanocytes. "Moreover, this signature has identified two tumor suppressor genes, DPP4 and SYK, whose downregulation has previously been implicated in melanoma development." (PMID 17611626, 2007). "Collectively, these results indicate that the activation of AKT3 mediated by SYK is crucial for the elevation of ROS and induction of cell death upon glucose deprivation in melanoma cells." (PMID 40774947, 2025). "In melanoma cells, the SYK-AKT axis played a critical role in ROS elevation and cell death during glucose deprivation." (PMID 40774947, 2025). "SYK expressed in melanocytes facilitates senescence and is lost in melanoma cells due to DNA methylation-mediated gene silencing." (PMID 29137391, 2017). "Other alterations were found in genes reportedly altered in skin cancer, such as DGKI and SYK in melanoma or BCOR, PIKFYVE and NEDD4 in SCC." (PMID 28410231, 2017). "If SYK inhibitors can effectively suppress the growth and survival of melanoma cells, SYK activity levels may serve as a biomarker for predicting treatment outcomes." (PMID 39026661, 2024). "Indeed, high ITH tumors were associated with significantly lower expression of lymphocyte-specific protein tyrosine kinase (LCK) (p = 2.3e−05) and spleen tyrosine kinase (SYK) (p = 0.0023) in melanoma cohort." (PMID 33344244, 2020). "In addition, genes with tumor suppressor and metastasis suppressor functions (DPP4, SYK) are included in this melanoma signature." (PMID 17611626, 2007). "Finally, for melanomas with acquired resistance to RAF inhibitors, DMEA identified CHK inhibitors and SYK inhibitors as potentially beneficial." (PMID 37226094, 2023).